CEBPA (CCAAT enhancer binding protein alpha)
Diseases named in the same sentence as CEBPA in open-access papers (continued):
Sharing a sentence is not in itself a finding about the gene and the disease.
glioma (29 papers, 2010 to 2024). A benign or malignant brain and spinal cord tumor that arises from glial cells (astrocytes, oligodendrocytes, ependymal cells). "Similarly, blocking the FTO/m6A/MYC/CEBPA-associated signaling pathway using R-2HG has shown promise in inhibiting the rapid development of glioma." (PMID 38649363, 2024). "The results revealed significantly reduced CEBPA and Galectin-9 expression levels in most glioma cells with 1p/19q codeletion." (PMID 34956239, 2021). "Compared with other tumor samples, CEBPA and Galectin-9 were most closely correlated in lower-grade glioma (LGG, WHO grades II and III)." (PMID 34956239, 2021). "PIWIL3 plus piR-30,188 and the PIWIL3/OIP5-AS1/miR-367-3p/CEBPA (CCAAT/enhancer-binding protein alpha) complex is involved in the pathogenesis of glioma." (PMID 33109195, 2020). "OIP5‐AS1 promotes glioma oncogenesis by sponging miR‐367‐3p to modulate the expression of CEBPA (CCAAT/enhancer binding protein alpha)." (PMID 32468629, 2020). "Other studies also show that FTO functions as an oncogenic role via maintaining the stability of transcripts of avian myelocytomatosis viral oncogene homolog (c-Myc) and CCAAT enhancer binding protein alpha (CEBPA) in glioma, especially IDH1/2 mutant glioma." (PMID 32244981, 2020). "We measured the mRNA expression of CEBPA and LOXL1 in 21 glioma specimens to determine the clinical relevance of our finding that LOXL1 was upregulated by CEBPA." (PMID 32424143, 2020). "We narrowed down 21 glioma specimens to 14 by selecting the samples with a better correlation between CEBPA and LOXL1 gene expression." (PMID 32424143, 2020). "For example, miR-367-3p is down-regulated in glioma and binds to 3’UTR of CEBPA to suppresse its expression, subsequently inhibiting the proliferation, migration and invasion of glioma cells." (PMID 32600379, 2020). "piR-30188 binds the lncRNA OIP5-AS1 and inhibits OIP5-AS1 expression, thereby suppressing glioma cell malignant phenotype via the miR-367/CEBPA/TRAF4 pathway." (PMID 31399034, 2019). "The PIWIL3/piR-30188/OIP5-AS1/miR-367-3p/CEBPA/TRAF4 pathway can regulate the biological behavior of glioma cells." (PMID 31399034, 2019). "Moreover, piR-30188 binds to a lncRNA OIP5-AS1 and inhibits its expression, leading to the suppression of glioma cell malignant phenotype via the miR-367/CEBPA/TRAF4 pathway." (PMID 38993562, 2024). "However, glioma cells with intact chromosome 1p/19q showed a significantly increased proportion of cells with high CEBPA and Galectin-9 expression levels." (PMID 34956239, 2021). "Among them, CEBPA played a key role in the regulation of Galectin-9 expression in gliomas." (PMID 34956239, 2021). "Studies also have shown that FTO may play an oncogenic role via maintaining the stability of transcripts of avian myelocytomatosis viral oncogene homolog (c-Myc) and CCAAT enhancer binding protein alpha (CEBPA) in glioma, especially IDH1/2 mutant glioma." (PMID 33718165, 2021). "As the most important transcriptional regulator of Galectin-9 in gliomas, the expression level of CCAAT enhancer-binding protein alpha in samples with 1p/19q codeletion was significantly decreased, which led to the downregulation of the immune checkpoints Galectin-9 and TIM-3." (PMID 34956239, 2021). "In detail, LOXL1 is upregulated by the VEGFR-Src-CEBPA axis in suspended glioma cells, and LOXL1 and BAG2 proteins can interact in glioma cells, preventing BAG2-K186 ubiquitylation depending on LOXL1 enzymatic activity and stabilizing BAG2 to ultimately promote cell survival." (PMID 32424143, 2020). "Similarly, OIP5-AS1 exerted oncogenic function via sponging miR-367-3p and increasing the expression of CEBPA in glioma cells." (PMID 30691465, 2019). "Therefore, PIWIL3/piR-30188 regulates the glioma cell malignant phenotype via the OIP5-AS1/miR-367/CEBPA/TRAF4 pathway." (PMID 31399034, 2019).
glioma (continued). "Low OIP5-AS1 expression increases miR-367-3p expression, thereby decreasing CEBPA, which facilitates glioma development by binding to the promoter of TRAF4 (which promotes cancer proliferation, migration, and invasion and inhibits apoptosis), ultimately weakening TRAF4 expression." (PMID 31399034, 2019). "R-2-hydroxyglutarate (R-2HG) has similar effects, which reduces MYC/CEBPA transcript stability and suppresses relevant pathways, with similar effects seen in glioma, suggesting R-2HG’s potential for targeting FTO/m6A/MYC/CEBPA signaling in FTO-high cancers." (PMID 39459530, 2024). "In this study, R-2HG was used to directly inhibiting FTO in AML and glioma cells, which resulted in increased methylation and decreased expression of c-MYC and CEBPA mRNAs, blocking proliferation, cell cycle, and inducing apoptosis in AML and glioma cells." (PMID 33461542, 2021). "FTO plays carcinogenic roles through maintaining the stability of gliomas, especially the stability of oncogene homologues (c-Myc) and CCAAT-enhancer-binding protein-α (CEBPA) transcripts in IDH1/2 mutant gliomas." (PMID 32943100, 2020). "CEBPA and TRAF4 are both over-expressed in glioma cells and tissues, and show a positive correlation with the pathological grade of glioma." (PMID 33109195, 2020). "A subset of 7 transcription factors (STAT3, BHLHE40, CEBPA and B, RUNX1, FOSL2 and ZNF238) controlled most genes of the mesenchymal signature of gliomas; all but ZNF238 were significantly upregulated in the group 2 tumours compared to the other DIPG." (PMID 22389665, 2012). "To further explore the specific molecular mechanism of this phenomenon, we assessed four transcription factors of Galectin-9 (AR, CEBPA, CEBPB, and TFAP2C) and found that CEBPA on chromosome 19q played a leading role in the transcriptional regulation of Galectin-9 in gliomas." (PMID 34956239, 2021). "Thereafter, a recent study showed that piR-30188 could regulate the expression of CEBPA by targeting lncRNA OIP5-AS1 at the post-transcriptional level, thus inhibiting the proliferation of glioma cells." (PMID 34803507, 2021). "Luciferase labeled glioma tumor cells with/without CEBPA knock down and T cells were mixed (1:1) and then transplanted into the intracranial of immunodeficient mice." (PMID 34956239, 2021). "After stratifying glioma samples according to WHO grade and 1p/19q codeletion status, we found lower expression levels of CEBPA, Galectin-9, and TIM-3 proteins in whole grade glioma samples with 1p/19q codeletion compared with those in samples with retained 1p/19q or normal tissues." (PMID 34956239, 2021). "In another study, PIWIL3/OIP5-AS1/miR-367-3p/CEBPA (CCAAT/enhancer binding protein alpha) feedback loop was found to regulate glioma cell growth, and the overexpression of PIWIL3 or piR-30188, either jointly or separately suppressed glioma progression." (PMID 33800703, 2021). "In the present study, under nonadherent conditions, the VEGFR/Src axis in glioma cells activates the transcription of the LOXL1 gene by increasing the binding of CEBPA to its promoter region." (PMID 32424143, 2020). "We surmise that the VEGFR-Src-CEBPA axis is important for upregulating LOXL1 expression in nonadherent cells, which in turn confers glioma cells the ability to resist apoptosis." (PMID 32424143, 2020).
myeloid neoplasm (27 papers, 2013 to 2025). Proliferation of myeloid cells originating from a primitive stem cell. "The 2016 revision to the World Health Organization classification of myeloid neoplasms includes two distinct CEBPA-related disease entities: AML with biallelic CEBPA mutations (CEBPABI) and AML with germline CEBPA mutations." (PMID 35967564, 2022). "In the list of germline mutations with predisposition to myeloid neoplasms, many encode known master transcription factors, such as CEBPA, RUNX1, and GATA2." (PMID 35054439, 2021). "Therefore, the 2016 WHO revision recognized AML with biallelic mutation of CEBPA as a distinct entity of AML, and AML with germline CEBPA mutation was placed under a separate subcategory of myeloid neoplasms with germline predisposition." (PMID 37261703, 2023). "However, in general, long-term remission can only be obtained by allogeneic HSCT, and HSCT should be considered soon after diagnosis of myeloid malignancy, except for cases with germline CEBPA mutations." (PMID 36185231, 2022). "Mutations in transcription factors such as CEBPA, RUNX1, and GATA2 can be seen in myeloid neoplasms, both de novo or with germline predisposition." (PMID 35054439, 2021). "In our study, olaparib upregulated RNA and protein expression of the granulocytic and monocytic transcription factors PU.1 and CEBPA, both proteins reported to be frequently downregulated in myeloid malignancies." (PMID 31527467, 2019). "In patients with myeloid neoplasms and germline predisposition without potential organ dysfunction (i.e., patients with germline mutation in RUNX1, DDX41, CEBPA and so on), no specific complication after HSCT has been reported till date." (PMID 36185231, 2022). "For example, microhomology-mediated recurrent deletions of CALR, ASXL1, and SRSF2 and non-recurrent deletions in TET2, DNMT3a, CEBPA, and RUNX1 have been reported in myeloid neoplasms." (PMID 36011278, 2022).
myeloid leukemia (21 papers, 2006 to 2025). A clonal proliferation of myeloid cells and their precursors in the bone marrow, peripheral blood, and spleen. "CN-AML was significantly found in AML patients aged ≥ 40 years, and mutation of NPM1 and CEBPA genes were significantly exhibited in this group, therefore these driven gene mutations were associated with myeloid leukemia development in the middle aged and the older patients." (PMID 30729065, 2019). "Decreased expression of CEBPA by posttranscriptional regulation was also shown in myeloid leukemia." (PMID 32877461, 2020).
liver cancer (20 papers, 2014 to 2026). An epithelial or non-epithelial malignant neoplasm that arises from the liver. "Wnt-βcatenin signaling controls CEBPA expression and transcriptional activity in liver cancer cells." (PMID 39991922, 2025). "In our work, we performed IP-mass and co-IP assays and identified the protein complex formed by TRIM71 with IGF2BP1, which stabilized CEBPA mRNA levels through an m6A-dependent manner in liver cancers." (PMID 39267787, 2024). "Based on our preclinical results, we suggest that ATRA combined with A-485 exert anti-tumor ability through repressing TRIM71/CEBPA expression and decrease serine/glycine metabolism in liver cancer." (PMID 39267787, 2024). "CEPBA knockdown significantly inhibited colony formation ability in highly expressed CEBPA liver cancer cells." (PMID 39267787, 2024). "By analyzing data from the Depmap database, we found a positive correlation between CEBPA mRNA expression and proliferative ability in liver cancer cell lines." (PMID 39267787, 2024). "Mechanistically, TRIM71 formed a protein complex with IGF2BP1, bound to and stabilized the mRNA of CEBPA in an m6A-dependent manner, enhance the serine/glycine metabolic pathway, and ultimately promoted liver cancer progression." (PMID 39267787, 2024). "Binding of the MBD2 protein with CCAAT/enhancer binding protein alpha (CEBPA) transcription factor enhances or suppresses expression of genes involved in liver cancer." (PMID 25340699, 2014). "Then we explored the function role of CEBPA in liver cancer cells." (PMID 39267787, 2024). "Conversely, PSPH and PSAT1 mRNA levels and protein levels were dramatically upregulated in TRIM71 and YAP5SA + TRIM71 mice liver tumor tissues compared to the control group, and inhibition of TRIM71 or CEBPA decreased cellular serine and glycine levels in HuH-7 and Hep3B liver cancer cells." (PMID 39267787, 2024). "Accumulating evidence has suggested that CEBPA has a pro-tumorigenic role in liver cancers." (PMID 39267787, 2024). "Indeed, CEBPα overexpression increased HMMR mRNA and protein expression in HepG2 and MHCC-97H liver cancer cells, and OA further promoted CEBPα-stimulated HMMR expression." (PMID 33061798, 2020). "TRIM71 forms a protein complex with IGF2BP1, enhances mRNA stability of CEBPA with m6A-dependent manner, remodels PSPH and PSAT1 transcription, strengthens serine/glycine metabolism, and ultimately promotes liver cancer progression." (PMID 39267787, 2024). "In tumors, TRIM71 stabilizes m6A-modified CEBPA mRNA dependent on IGF2BP1, and ultimately facilitates liver cancer progression." (PMID 39267787, 2024). "TRIM71 binds to and stabilizes the mRNAs of CEBPA, remodels PSPH and PSAT1 transcription, enhances the serine/glycine metabolic pathway, and ultimately promotes liver cancer progression." (PMID 39267787, 2024). "In this study, we clarified that HAL was transcriptionally induced by CEBPA and FOXA1, and that their expression levels were down-regulated by the Wnt/β-catenin signaling in the liver cancer cells." (PMID 38684876, 2024). "In this study, we have shown that the promoter region of HAL was transcriptionally regulated by transcription factors CEBPA and FOXA1, and that the two were down-regulated by the Wnt signaling pathway in the liver cancer cells." (PMID 38684876, 2024). "Small activating RNAs (saRNAs) can upregulate CEBPA mRNA in human HCC cells and inhibit the growth of liver cancer." (PMID 36726725, 2023). "Importantly, ATRA or A-485 decreased mRNA levels of TRIM71, CEBPA, PSPH, PSAT1 and protein levels of TRIM71 and CEBPA, suggesting the transcriptional regulation of RXRA and EP300 to TRIM71 in liver cancer." (PMID 39267787, 2024). "Interestingly, both ATRA and EP300 inhibitor A-485 could decrease TRIM71 and CEBPA expression and dampen glycine/serine metabolism, and ATRA could enhance anti-tumor ability of A-485 in liver cancer." (PMID 39267787, 2024).
liver cancer (continued). "Importantly, it forms a protein complex with IGF2BP1, which binds to and stabilizes CEBPA mRNA levels through an m6A-dependent manner, enhancing CEBPA mediated PSPH/PSAT1 transcription and remodeling serine/glycine metabolism, and ultimately accelerates liver cancer growth and tumorigenicity." (PMID 39267787, 2024). "To determine whether the NHL domain regulates CEBPA expression and mediates the oncogenic function of TRIM71, we first infected liver cancer Li-7 cells with a TRIM71 lentiviruses lacking the NHL domain." (PMID 39267787, 2024).
acute promyelocytic leukemia (19 papers, 2009 to 2026). An aggressive form of acute myeloid leukemia (AML), characterized by arrest of leukocyte differentiation at the promyelocyte stage, due to a specific chromosomal translocation t(15;17) in myeloid cells. "Decreased expression of CEBPA plays a role in acute promyelocytic leukemia (APL) leukemogenesis." (PMID 31141090, 2019). "The transformation of acute promyelocytic leukemia (APL) to acute mononuclear leukemia during treatment is a rare clinical phenomenon, and no CCAAT/enhancer-binding protein alpha (CEBPA) double mutations have been reported." (PMID 33592885, 2021).
diabetes (19 papers, 2010 to 2024). "CEBPα binds to the Ly6c promoter and its expression was elevated and synergistically increased in HHcy and Type 2 Diabetes Mellitus mice." (PMID 33717169, 2021). "We confirmed that TF CEBPα binds to the Ly6c promoter and that its expression was elevated and synergistically increased in HHcy and Type 2 Diabetes Mellitus mice, supported the note that TF CEBPα transactivates Ly6c gene and mediates inflammatory MC subset differentiation." (PMID 34987524, 2021). "Among them, CEBPA and CEBPB are adipogenic transcription factors that not only impact adipogenesis but also influence the occurrence of diabetes." (PMID 39553470, 2024).
steatosis (16 papers, 2014 to 2026). Increased lipid within the cytoplasm of cells. "H&E staining of the livers of CEBPα-S193D mice revealed that they develop steatosis in the NH arm and severe steatosis in the HH arm." (PMID 37967813, 2024). "Homozygous deletion of CEBPA is postnatally lethal due to hypoglycemia, whereas liver-specific conditional knockout of CEBPA results in glucose intolerance and steatosis." (PMID 32623605, 2020). "Importantly, while circulating lipid levels could be rescued by CEBPA knock-out, hepatic lipid accumulation (steatosis) could not, indicating that TRIB1 has roles transcending CEBPA regulation." (PMID 28717196, 2017).
lung adenocarcinoma (15 papers, 2012 to 2024). A carcinoma that arises from the lung and is characterized by the presence of malignant glandular epithelial cells. "In solid tumors, CEBPA alterations were most frequently observed in lung adenocarcinomas, consisting primarily of mutations followed by amplifications, missense, frameshift, insertion, and loss." (PMID 38164123, 2024). "When fully functional and overexpressed, the CEBPA transcription factor was shown in cell culture to inhibit migration and invasion of lung adenocarcinoma by suppressing epithelial‐to‐mesenchymal transition and the Wnt/beta‐catenin pathway." (PMID 38164123, 2024). "The CEBPB promoters were unmethylated in all lung adenocarcinoma samples with available methylation data (n = 185), whereas the CEBPA promoter regions were frequently aberrantly methylated, consistent with previous results." (PMID 25767874, 2015). "The expression of some genes known to be c-Myc-responsive such as CEBPα was oppositely regulated in lung adenocarcinomas when compared with previously reported studies, therefore pointing to tissue-specific responses to c-Myc activity." (PMID 26427040, 2015).
Myelodysplasia (14 papers, 2017 to 2025). Clonal hematopoietic stem cell disorders characterized by dysplasia (ineffective production) in one or more hematopoietic cell lineages, leading to anemia and cytopenia. "As such, the presence of del(9q) was also removed as a defining myelodysplasia-related cytogenetic abnormality because its association with NPM1 and biallelic CEBPA mutations." (PMID 32722092, 2020). "All these patients had mutated NPM1 with a low allele ratio of FLT3-ITD, three patients also had one or more myelodysplasia-related gene mutations, and one patient also had a biallelic but non-bZIP CEBPα mutation." (PMID 38609396, 2024). "Familial AML with germline CEBPA mutations (FAML-CEBPA) generally present without preceding abnormal blood counts or myelodysplasia." (PMID 37261703, 2023). "This change was based on emerging data showing that multilineage dysplasia in the absence of myelodysplasia-related cytogenetic changes did not appear to associate with poor prognosis in the presence of an NPM1 mutation or biallelic CEBPA mutation." (PMID 32722092, 2020).